IL7 (interleukin 7)
Diseases named in the same sentence as IL7 in open-access papers (continued):
Sharing a sentence is not in itself a finding about the gene and the disease.
tumor (continued). "Interestingly, tumor expression of IL7 was not only associated with pathways involved in immune response but with increased overall survival of patients." (PMID 36054746, 2022). "These contradictory findings indicate that more research is needed to determine whether IL-7 functions as a promoter or inhibitor of tumor growth, but they also highlight IL-7’s association with tumor development." (PMID 35794603, 2022). "Taken together, the loss of IL-7, IL-15, and IL-18 may be playing a role in the decreased numbers of lymphocytes in the tumor microenvironment, which supports a protumorigenic environment." (PMID 33290281, 2021). "A study ascertained whether administration with OVA-NPs trapping IL-7 (OVA-NPs-IL-7) is able to cause anti-tumor immune responses in vivo." (PMID 34835555, 2021). "However, it has been shown that in tumor cells IL-7 is associated with increased aggressiveness of solid tumors and enlarged metastasis rate." (PMID 33791196, 2021). "These modifications of a Tfh-functional phenotype in FL could be in turn fostered by tumor cells through their increased expression of IL-6 and IL-7, both implicated in T cell homeostasis, memory T cell generation, and Tfh activation." (PMID 33028033, 2020). "Moreover, the upregulation of MMP-9 expression and activity is associated with tumor angiogenesis, invasion, and metastasis when IL-7 is overexpressed as well." (PMID 31185636, 2019). "Preclinical models have demonstrated that interleukin-7 (IL-7) and IL-15 administration to irradiated mice resulted in greater tumor regression which was associated with an increase in CD8+ cytotoxic T cell counts without an increase in immunosuppressive regulatory T cell counts." (PMID 30613390, 2018). "To better define the mechanisms underlying the tumor-supportive function of Il7-expressing CAFs, we compared the gene expression profiles of sorted EYFP+PDPN+ (designated ‘EYFP’) and EYFP−PDPN+ (designated ‘PDPN’) CAFs from E0771 tumors growing in Il7-EYFP mice." (PMID 29632733, 2018). "Moreover, when co-examined in two-way ANOVA, both lymph node involvement (F = 5.29, p = 0.023) and tumor location (F = 6.35, p = 0.013) were significantly and independently from each other associated with IL-7." (PMID 27866242, 2017). "Since IL-7 promotes T cell survival, activation, proliferation and memory T cell (TM) formation its direct action on T cells is supposed to be the major cause for its potent anti-tumor effects." (PMID 27447484, 2016). "Tumor-selective vaccinia viruses encoding IL-7 and IL-12 have previously been reported; however, the short replication cycle of vaccinia viruses makes it difficult, in some cases, for them to secrete sufficient inflammatory cytokines to inhibit tumor growth prior to viral elimination." (PMID 37835433, 2023). "Precise mechanisms underlying interleukin-7 (IL-7)-mediated tumor invasion remain unclear." (PMID 31061414, 2019). "Research has demonstrated that IL-7-expressing fibroblasts are localized to the tumor border and physically interact with cancer cells, thereby promoting cancer stem cell and lymphoid development through the activation of JAK-STAT5 signaling." (PMID 41597220, 2026). "By the 48-hour timepoint, IL-7–ALT T cells made up approximately 20% of all T cells in tumor, (mean 18.8%, SD ±4.3%, n = 5), while the fraction of T cells that consisted of IL-2 ALT in tumors was approximately 1% (mean 1.7%, SD ±1.5%, n = 4)." (PMID 40244705, 2025). "We therefore returned to further investigate our initial IL-7–ALT method for enhancing T cell numbers in tumor." (PMID 40244705, 2025). "To assess the cytotoxicity of IL-7-CAR-T cells against tumor cells, we conducted a luminescent assay at various effector-to-target (E:T) ratios." (PMID 41450878, 2025). "The regulatory role of IL-7 in immune cells—mediated by its binding to the receptor IL7R—has been extensively studied, and emerging evidence indicates that IL-7/IL7R signaling modulates tumor-immune interactions." (PMID 41360767, 2025).
tumor (continued). "The local expression of IL-7 alone, and in combination with other cytokines and chemokines, remodels the TME and enables tumor susceptibility to immunotherapy." (PMID 40957993, 2025). "This process fosters a dynamic microenvironment marked by tissue repair and the presence of mediators such as IL-1, IL-10, and IL-7, which bolster the immune response and enhance therapeutic efficacy while mitigating tumor regrowth." (PMID 40420174, 2025). "Treatments used have included, sequentially: vinorelbine/oral cyclophosphamide/bevacizumab, vincristine/dactinomycin, topotecan/cyclophosphamide, vincristine/topotecan/doxorubicin, or autologous tumor cell vaccine supported by IL-7 and pazopanib." (PMID 41356919, 2025). "Transcriptional analysis of hPBMCs expanded with IL-7 reveals upregulation of genes involved in integrin expression and tumor infiltration (e.g., CD9, VLA-6, EPHA4)." (PMID 40244705, 2025). "By 48 hours after administration, we detected an increased proportion of the IL-7–ALT dose within tumor compared to IL-2–ALT." (PMID 40244705, 2025). "IL-7 also exerts tumor-promoting effects by activating the downstream PI3K-AKT pathway and has been utilized in clinical research." (PMID 41179658, 2025). "Other studies have also demonstrated that the co-expression of IL-7 with CCL21 or CCL9 on CAR-T cells boosts their anti-tumor capabilities." (PMID 41450878, 2025). "Counts of IL-7–ALT CD8+ T cells in tumor were also increased compared with IL-2 ALT throughout, though differences were nonsignificant." (PMID 40244705, 2025). "Here, we investigated the molecular design of tumor-directed trifunctional antibody-cytokine fusion proteins for a combinatorial approach of IL-15 with either IL-7 or IL-21." (PMID 40370435, 2025). "Sorted CD8+ T cells were expanded with IL-2 or IL-7 and cocultured with tumor only (U87vIII); tumor + BRiTE; or phorbol myristate acetate (PMA)/ionomycin." (PMID 40244705, 2025). "The combination of IL-7-CAR-T cells with either C8A8 or Nivo resulted in a significant reduction in tumor growth since day 21, compared to the control group." (PMID 41450878, 2025). "Molecular studies on tumor tissues showed an increase in the local expression of IL-7 and the number of CD8+ T cells in the CTSS-knockdown group, which was counteracted by αIL-7." (PMID 40707961, 2025). "IL-7 is known to promote the survival of tumor-specific T cells, and preclinical studies have shown that genetically modification to enhance IL-7 signaling, either through secretion or receptor overexpression, can significantly boost their anti-tumor efficacy." (PMID 41153826, 2025). "IL-7 protects the survival of tumor-reactive memory T-cell clones, while GM-CSF recruits and licenses myeloid sentinels to break down immunosuppressive barriers." (PMID 40299475, 2025). "Interleukin-7 (IL-7), a critical cytokine in adaptive immunity, has been extensively utilized to amplify tumor-targeting T-cell functionality, with pronounced effects on CD8+ cytotoxic T lymphocyte activation and persistence." (PMID 40299475, 2025). "CD8+ effector and tissue-resident T cells expressed numerous IL-related receptor genes; however, they lacked stimulation from IL-related cytokines such as IL-2, IL-4, IL-7, and IL-15 when comparing response states between tumor and healthy groups." (PMID 40698080, 2025). "To assess the proliferative capacity of IL-7-CAR-T cells within the tumor microenvironment, we injected 2.5 × 106 cells (NT, CAR-T, or IL-7-CAR-T) into pre-established tumor sites using intratumoral injection." (PMID 41450878, 2025). "Here, we report the design of novel trifunctional tumor-directed antibody-cytokine fusion protein formats combining IL-15 with IL-21 or IL-7." (PMID 40370435, 2025). "Four days later, tumor-bearing mice received intravenous injections of either 1 × 107 CAR-T or IL-7-CAR-T cells." (PMID 41450878, 2025).
tumor (continued). "This study aimed to investigate the mechanism by which tumor CTSS affects anti-tumor immunity through the regulation of interleukin-7 (IL-7) to overcome this obstacle." (PMID 40707961, 2025). "In our study, the combination of anti-PD-1 antibody with IL-7-CAR-T cells effectively enhanced the tumor-killing efficacy of CAR-T cells." (PMID 41450878, 2025). "A SINV co-expressing IL-7 plus IL-12 (SINV-IL7/IL12) further enhanced tumor suppression compared to SINV-IL7 or SINV-IL12, with SINV-IL7/IL12 achieved 80% long-term survivors in an intracranial U-87MG GBM model." (PMID 40957993, 2025). "This study aimed to investigate the mechanism by which CTSS mediates IL-7 secretion and its impact on anti-tumor immunity and to evaluate the potential of RJW-58 to support the anti-PD-1 antibody (αPD-1)." (PMID 40707961, 2025). "Compared to NT and conventional CAR-T cells, the IL-7-CAR-T cells exhibited significantly greater T-cell expansion within the tumor, indicating enhanced local persistence and proliferation." (PMID 41450878, 2025). "The CTSS-targeting strategy has the potential to reinvigorate IL-7-directed anti-tumor T cell immunity and enhance the therapeutic effect of the anti-PD-1 antibody." (PMID 40707961, 2025). "Mice treated with IL-7/IL-12-engineered MSCs in combination with CAR T cells exhibited significantly reduced tumor growth." (PMID 40643499, 2025). "Both heparanase-expressing CAR T-cells and hyaluronidase-expressing CAR T-cells have demonstrated increased tumor infiltration and enhanced anti-tumor activity, including when hyaluronidase and IL-7 armoring were combined." (PMID 41019052, 2025). "Although no head-to- studies have been conducted comparing the effects of IL-7 vs IL-15 to increase tumor trafficking, IL-15 can also strongly enhance tumor trafficking via its effects to increase lymphocyte adhesion molecules and chemokines." (PMID 41550947, 2025). "For instance, Vera and colleagues improved CAR T-cell function by introducing an IL-4/IL-7 invert cytokine receptor (ICR) to counteract the immunosuppressive tumour microenvironment in pancreatic cancer." (PMID 40335685, 2025). "Therapeutically, the B16-LX/IL-7 vaccine significantly inhibits homologous B16-F10 tumor growth compared to the non-IL-7-expressing B16-LX/RFP vaccine." (PMID 40957993, 2025). "Our previous studies have shown that the addition of IL-7 and IL-15 significantly improves the anti-tumor effect of CAR-T cells." (PMID 41450878, 2025). "These CD4+ T cells were ex vivo expanded with the treatment of Δ35 mM NaCl, anti-CD3/CD28, IL-2 and IL-7 along with heat-killed tumor cells." (PMID 40563574, 2025). "While the C8A8 antibody combined with IL-7-CAR-T cell therapy has shown promising anti-tumor activity in NSCLC treatment, further optimization is needed to improve therapeutic efficacy." (PMID 41450878, 2025). "100% of the tumor-free mice due to Ad.IL-7/B7.1 treatment rejected TS/A tumor rechallenge, likely due to the treatment-induced immunological memory." (PMID 40957993, 2025). "The engineered co-expression of GM-CSF and IL-7 correlated with enhanced viral replication efficiency in tumor cells." (PMID 40299475, 2025). "Our experimental data demonstrate that the simultaneous delivery of GM-CSF and IL-7 potentiates vaccinia virus (VV)-mediated tumor regression through increased infiltration and functional activation of tumor-associated immune cell populations." (PMID 40299475, 2025). "VVL-GL7 showed the strongest and most durable anti-tumor effect, with a higher percentage of mice achieving complete tumor clearance compared to viruses containing either GM-CSF or IL-7 alone." (PMID 40299475, 2025). "The administration of the recombinant IL-7 protein reduced tumor burden with extensive lymphocytic infiltration of the tumor and enhance survival through the CXCR3 signaling pathway in lung cancer-bearing mice." (PMID 40707961, 2025).
tumor (continued). "Following tumor establishment, NT, IL-7-CAR-T cells, and anti-PD-1 antibodies were administered intravenously to the tumor-bearing mice, with tumor progression monitored at various time points." (PMID 41450878, 2025). "This shift will increase the immunosuppressive cytokines (IL-2, IL-4, IL-7, IL-13, and IL-15) production by neoplastic elements which lead to tumor growth and spread." (PMID 38850434, 2024). "This review aims to discuss the origin of IL-7 and its receptor IL-7R, its anti-tumour mechanism, and the recent advances in the application of IL-7 in tumour therapy." (PMID 38675377, 2024). "Studies have demonstrated that IL-7 not only promotes Th17 cell proliferation to enhance anti-tumour efficacy in a mouse B16F10 tumour model but also is necessary for developing effector Th17 cells into resident memory T cells." (PMID 38675377, 2024). "Here, we show that IL7 in combination with radiotherapy (RT) is effective in activating CD8 + T-cells for reducing tumor growth." (PMID 38554147, 2024). "The higher motility of IL7/15 CD8+ T cells compared to IL2 cells was also confirmed in tumor slices derived from the BxPC3-NSG model." (PMID 38467616, 2024). "Based on the powerful immunomodulatory effects of IL-7, which can act directly or indirectly on tumour cells, IL-7 can effectively reduce the tumour load in tumour therapy and exert anti-tumour effects by enhancing eradication or adaptive immunity." (PMID 38675377, 2024). "The results of a large number of preclinical and clinical studies have shown that IL-7 can enhance anti-tumour efficacy by promoting lymphocyte infiltration and improving the tumour microenvironment." (PMID 38675377, 2024). "Scientists have therefore extended its half-life by genetically engineering it to fuse with the c-terminal end of hIgG1 Fc to enhance IL-7 activity to increase the immune effect of IL-7 in tumour therapy." (PMID 38675377, 2024). "Tumor proteomics showed a strong effect of RT, alone or in combination with IL7, as represented by unsupervised principal component analysis (PCA)." (PMID 38554147, 2024). "In this paper, we analyzed scRNA-seq data from human cancers and a mouse tumor transplant model and assessed the treatment efficacy of recombinant IL-7 (rIL7) in a mouse model." (PMID 38424167, 2024). "We show that IL7 in conjunction with RT works to decrease tumor growth through stimulation and maintenance of a memory T-cell phenotype, notably without a parallel increase in Treg influx into the tumor microenvironment (TME)." (PMID 38554147, 2024). "IL-7, which has demonstrated strong effectiveness in fighting tumours when used alone, can also be utilised in combination with other cytokines such as IL-12, IL-15, and GM-CSF." (PMID 38675377, 2024). "In this study, we have demonstrated that IL-12/IL-7/IFN-α mRNA triplet induces much higher anti-tumor potency, compared with that induced by anti-PD-1/PD-L1 therapy in both syngeneic and humanized mouse models." (PMID 39290693, 2024). "Our experiment on the mouse model demonstrated that recombinant IL-7 therapy induces tumor regression, expansion of effector CD8 T cells, and pro-inflammatory activation of macrophages." (PMID 38424167, 2024). "The tumor volume in mice receiving C5/IL7-CAR-T cells was significantly smaller than that in mice treated with wild-type CAR-T cells, together with an increased number of CAR-T cells at the tumor sites." (PMID 39450160, 2024). "Utilizing single-cell transcriptome technologies, we have deepened our understanding of the anti-tumor effects of IL-7 and discovered new strategies for employing IL-7 in anti-cancer therapy." (PMID 38424167, 2024). "It is fascinating to learn about the potential of IL-7 in immune reconstitution and its anti-tumour activity based on preclinical studies." (PMID 38675377, 2024).
tumor (continued). "Human interleukin-7 (IL-7) is a pleiotropic immune cytokine that exerts both direct and indirect effects on anti-tumor activity and impacts the growth, survival, and differentiation of B and T cells." (PMID 39093440, 2024). "IL-7 has a promising application in tumour immunotherapy because of its antagonistic effect on the state of immunosuppression." (PMID 38675377, 2024). "Treatment with RT and IL7 (RT + IL7) resulted in significant tumor growth reduction, high CD8 T-cell tumor infiltration, and increased proliferation of T-cell progenitors in the bone marrow." (PMID 38554147, 2024). "FOXP1 was also reported to act as a tumor suppressor via the negative regulation of the expression of IL-7 in tumor-specific CD4 + T helper cells 7 (Th9)." (PMID 38279090, 2024). "Although not pursued in our study, tumor antigens can be addressed using effector T cell clones expanded at the tumor site by IL-7 treatment." (PMID 38424167, 2024). "Examining the differences between tumor growth in the IL7 alone group compared to the RT + IL7 group provides insight into immunotherapy design." (PMID 38554147, 2024). "The search strategy included (but was not limited to) the following terms: cytokines, IL-7, cancer therapy, tumours, malignant stroma, clinical data, and combination therapy." (PMID 38675377, 2024). "In summary, our data show that IL7 in combination with radiotherapy provides a novel treatment regimen that can control tumor growth in HNSCC preclinical models." (PMID 38554147, 2024). "Adjuvant IL-7 enhanced T cell effector function by increasing IL-6 production and T helper type 17 cell differentiation, resulting in improved anti-tumor responses and overall survival." (PMID 38424167, 2024). "It is important to point out that modifying MSCs genetically to increase the expression of IL-7 and IL-12 can alter the chronic inflammatory milieu into a more anti-tumor-responsive Th1/Th17 TME." (PMID 38314300, 2024). "Coadministration of RT and IL7 (RT + IL7) was found to significantly reduce tumor growth and prolong overall survival compared to RT or IL7 alone." (PMID 38554147, 2024). "The tumour growth rate was significantly reduced, and survival was improved in the treatment group receiving intravenous IL-7." (PMID 38675377, 2024). "Contrarily, the pro-tumor effect of IL-7 depends on the direct interaction of this cytokine with its receptor on cancer cells, thus promoting tumor growth." (PMID 38835768, 2024). "Based on the functional enrichment analyses, LSAGs were associated with binding and molecular activity functions, inhibition of DNA damage repair and tumor growth, IL7 signaling pathway, and glycolysis." (PMID 38509982, 2024). "It is worth noting that IL-7 inhibits tumour growth by regulating the proportion of immune iso-cell infiltration in the tumour immune microenvironment." (PMID 38675377, 2024). "IL-12 and IL-7 synergistically induce T cell activation and NK cell maturation, leading to potent anti-tumor activity." (PMID 39290693, 2024). "The anti-tumor activity of IL-12/IL-7/IFN-α mRNA triplet was investigated in subcutaneous syngeneic tumor-bearing mice." (PMID 39290693, 2024). "In one study, i.t. injection of a tumor-selective VV encoding IL-7 and IL-12 (hIL-7/mIL-12-VV) had considerable antitumor effects in B16F10, CT26, and LLC models, and even distant tumor suppression." (PMID 39451566, 2024). "Previous research has demonstrated that IL-7 influences tumor cell proliferation and transmission, lymphocyte production and differentiation in the thymus and bone marrow, and peripheral naive and memory T cell survival." (PMID 38745115, 2024). "Intratumoral injection of LNP-encapsulated IL-12/IL-7/IFN-α mRNA triplet significantly increased cytokine expression in the tumor tissues." (PMID 39290693, 2024). "Direct delivery of dex and IL-7 into tumor-bearing mice resulted in increased persistence of adoptively transferred CAR T cells and complete tumor regression." (PMID 38140726, 2024).